CXCL12 (C-X-C motif chemokine ligand 12)
Diseases named in the same sentence as CXCL12 in open-access papers (continued):
Sharing a sentence is not in itself a finding about the gene and the disease.
colon carcinoma (77 papers, 2007 to 2025). "Treatment of NK cells with CXCL12 or ceralifimod was also linked to poorer outcomes in killing the colon cancer cell line HCT-116." (PMID 40155684, 2025). "The purpose of this study was to investigate the effect of CXCL12 gene silencing on metastatic potential and the underlying mechanism in colon cancer cells." (PMID 29305742, 2018). "Aberrant gene silencing in tumor cells is often associated with gene promoter methylation, and CpG island methylation has been suggested to be a primary cause of the decay of CXCL12 expression in several cancers, including colon cancer." (PMID 28418886, 2017). "We also demonstrated that loss of PCAF expression is an early event in colon cancer initiation, observed at the adenoma stage and maintained in carcinomas that correlates with CXCL12 silencing in human tumors." (PMID 28418886, 2017). "In these CRCs tissues, an analysis of the expression of 85 genes regulating epigenetic processes showed a loss of expression of a histone acetyltransferase, the protein P300/CBP-associated factor (PCAF), and forced expression of PCAF in colon cancer cell lines restored the expression of CXCL12." (PMID 35406582, 2022). "In this study, it was found that the AT events of CXCL12 may be the major AS events affecting the prognostic risk of colon cancer to a large extent, and patients with higher CXCL12_AT_11344 PSI had better prognoses." (PMID 35126520, 2022). "The results clearly confirm previous work showing that a loss of CXCL12 expression is a hallmark of colon cancer and in addition, we demonstrate for the first time, that the loss occurs early in the colon pathogenesis process as it is already present in the adenomas." (PMID 28418886, 2017). "The CXCL12/CXCR4 axis is a critical target for inflammation-driven CRC progression, and high CXCR4 expression in patients with colon cancer increases the risk of recurrence and poor survival." (PMID 39804065, 2025). "It reduces the levels of pro-inflammatory cytokines (e.g., IL-6 and TNF-α) and pro-carcinogenic cytokines (TGF-β1, TNF-β, and CXCL12) which exerts an inhibitory effect on pancreatic cancer associated fibroblasts (CAF) and colon cancer (HCT 116) cells." (PMID 40490812, 2025). "CXCL12 is constantly produced in the lungs, bone marrow and liver, which is one of the main organs affected by colon cancer metastasis." (PMID 40943634, 2025). "In colon cancer, CXCL12 induced transcriptional down-regulation of activated PTEN promoting cell survival." (PMID 38704478, 2024). "CXCL12 gene expression was drastically downregulated in primary colon cancer (Log2FC = −3.1), but its expression level increased in metastatic cancer vs. primary, Log2FC = 1.03." (PMID 39409185, 2024). "CXCL6 and CXCL12 promoted the metastasis of colon carcinoma by cooperatively activating the PI3K/Akt/mTOR pathway." (PMID 37491836, 2023). "A study found that treatment with CXCL12 prompted CTLs to leave cutaneous tumors via lymphatic vessels, whereas suppression of CXCL12 expression in senescent tumor cells enhanced T cell infiltration in colonic tumors." (PMID 37426662, 2023). "This downregulation of CXCL12 expression also prevents colonic tumor cells from undergoing anoikis, a form of apoptosis when cell–cell contact is lost between epithelial cells." (PMID 35406582, 2022). "The difference in effects of CXCL12M (e.g., the CXCL12-H25R mutant) and CXCL12D (disulfide-linked) on the migration of colon cancer HCT116 and HT29 and monocytic leukemia THP-1 cells was previously observed." (PMID 36229490, 2022). "Studies have shown that CXCL12 is expressed in the cytoplasm and cell membrane of colon cancer cells, as well as in fibroblasts in tumor stroma." (PMID 34930323, 2021). "This increase in the levels of CXCL12 and TGF-α is associated with an increased risk of colon cancer development." (PMID 35582377, 2021).
colon carcinoma (continued). "To analyze the effects of CXCL12 on CD8+ T cell infiltration using an in vivo animal model, we transplanted mouse CXCL12 (mCXCL12) overexpressing MC38 murine origin colon cancer cells into C57BL/6 mice." (PMID 33643790, 2021). "The effects of IL-1α and its receptor antagonist IL-1Ra on the migration of colon cancer cells and promoting angiogenesis and the chemotaxis of CXCL12 all play an important role in tumorigenesis and metastasis." (PMID 34930323, 2021). "Our previous studies have found that CXCL12 can also enhance the invasiveness of colon cancer cells and significantly promote the proliferation and migration of human umbilical vein endothelial cells." (PMID 34930323, 2021). "The chemotactic cytokine CXCL12 is expressed constitutively in lung, bone marrow, and liver, the most common sites for colon cancer metastasis." (PMID 34298991, 2021). "Previous evidence demonstrated that Pep R reduced the CXCL12 mediated internalization in HCT116 human colon cancer cells, possibly adding this effect to transcriptional downregulation." (PMID 32708431, 2020). "Human colon cancer tissue, spleen tissue and lymph node tissue were used as CXCL12 CXCR4 and CXCR7 positive control, respectively, the Goat‐isotype and rabbit isotype antibody were used as negative control for placenta tissues." (PMID 31991051, 2020). "While the inhibition of CXCL12 and CXCR4 can signifcantly reduce tumor cell proliferation and metastasis, indicating that CXCL12 is closely related to development, outcome and prognosis of colon cancers." (PMID 31500630, 2019). "Stromal-derived CXCL12 play an important role which influence the proliferation and invasiveness of colon cancer in microenvironment." (PMID 31500630, 2019). "The Akt kinase activity of colon cancer cells was remarkably enhanced by CXCL12 stimulation in a time-dependent manner." (PMID 31500630, 2019). "As key signaling molecules in tumor microenvironment, the fibroblast-derived CXCL12 has been shown to play an important role in the development of colon cancer." (PMID 31500630, 2019). "The silencing CXCL12 gene significantly inhibits the proliferation, invasion and angiogenesis ability of some types colon carcinoma cells through down-regulation of MAPK/PI3K/AP-1 signaling pathway." (PMID 29305742, 2018). "CXCL12 gene silencing resulted in blockage of MAPK, PI3K and AP-1 phosphorylation by CXCL12-induced in DLD-1 colon cancer cell." (PMID 29305742, 2018). "CXCL12 mRNA was expressed only in DLD-1 colon cancer cell line, while CXCR4 mRNA was expressed in four colon cancer cell lines." (PMID 29305742, 2018). "WST-1, invasion and angiogenesis assay were used to examine the effect on proliferation, invasion and angiogenesis in colon cancer cells after CXCL12 siRNA silence, respectively." (PMID 29305742, 2018). "This is consistent with the results of a related study which showed that CXCL12 can enhance the metastases of colon cancer." (PMID 29305742, 2018). "RT-PCR and Western-blot were used to detect the expression of CXCL12 mRNA and protein in four colon cancer cell lines." (PMID 29305742, 2018). "As verified by MS-PCR, SW480, HCT116 and TC7 human colon cancer cells are characterized by different CpG island methylation profiles at the CXCL12 locus and at five additional genes, known to specify the methylator phenotype." (PMID 28418886, 2017). "Although the mechanistic link between CXCL12 silencing, the default promoter histone acetylation and colon cancer formation and progression require further investigation, the results of our study are of potential clinical interest." (PMID 28418886, 2017). "CXCL12 has been shown to be involved in colon cancer metastasis, but its expression level and molecular mechanisms regulating its expression remain controversial." (PMID 28418886, 2017).
colon carcinoma (continued). "Altogether, in our model of colon cancer cells, defect of histone acetylation would be a major epigenetic mechanism for CXCL12 downregulation, alone or in combination with promoter hypermethylation." (PMID 28418886, 2017). "In conclusion, besides confirming a major decrease of CXCL12 expression in carcinomas as already shown in colon cancer, we demonstrate that the decrease is a precocious event occurring already in adenomas." (PMID 28418886, 2017). "In breast and colon cancer, lower intrinsic levels of the chemoattractant chemokine CXCL12 due to hypermethylation of its promoter disrupt cellular feedback mechanisms to internalize membranous CXCR4." (PMID 27462860, 2016). "The stimulation of F-actin polymerization in the context of CXCL12 in these cells was reminiscent of that observed during CXCL12-mediated cell motility of HCT116 colon-carcinoma cells." (PMID 25884570, 2015). "Given that CXCL12 can stimulate or repress cell motility in a dose-dependent manner in monocytic leukemia and colon cancer cell lines, we wanted to determine the CXCL12 concentration that is optimal for stimulating CXCR4-mediated motility in LNCaP cells." (PMID 25884570, 2015). "In human colon carcinoma cells we determined that re-expression of CXCL12 restored sensitivity to detachment-induced apoptosis, a key molecular brake preventing dissemination of cancer cells." (PMID 24594697, 2014). "The overarching goal of the following studies was to unravel the biochemical and cellular mechanisms through which CXCL12 induces anoikis in colonic carcinoma cells." (PMID 20877573, 2010). "Recent studies have also demonstrated that the CXCL12 gene modulates metastatic potential in breast and colon carcinomas, where it controls its own regulation in an autocrine loop." (PMID 20109227, 2010). "Samples of HER1-positive colon cancer metastases in liver, a tissue with high expression of CXCL12, were analysed by immunohistochemistry." (PMID 20946648, 2010). "One hypothesis is that prior to the development of metastasis, many colon cancer cells (CRCs) undergo DNA hypermethylation within the CXCL12 promoter, leading to reduced autocrine and paracrine CXCL12 signaling." (PMID 40943634, 2025). "Moreover, CXCL12 gene silencing significantly inhibited the proliferation and invasion of colon cancer DLD-1 cells by down-regulating the MAPK/PI3K/AP-1 signaling pathway." (PMID 37497001, 2023). "Besides, CXCL12-KDEL retention protein was used to block colon cancer cells, resulting in repression of the signaling involved in CXCR4 and a significant reduction in the metastatic cancer growth." (PMID 35388021, 2022). "Likewise, reduction of CXCR4 expression by siRNA in human colonic tumor cells cultured in hypoxia decreases CXCL12-induced phosphorylation and activation of Akt, while ERK activation is unchanged." (PMID 35406582, 2022). "In addition, we found that miR‐126‐overexpressing colon cancer cells inhibited macrophage recruitment, whereas miR‐126‐silenced cells promoted macrophage recruitment, and the CXCL12/CXCR4 axis mediated the regulatory effects." (PMID 35363937, 2022). "Furthermore, suppression of CXCR4 led to down-regulation of invasion induced by the C-X-C chemokine ligand 12 (CXCL12) ligand in HCT116 colon cancer cells." (PMID 33801741, 2021). "Besides, CXCL12 can trigger anti-apoptotic and proliferative signals in colon cancer cells by inducing mononuclear phagocytes to release HB-EGF, which binds the Epidermal Growth Factor Receptor (EGFR/HER1) and stimulates its signaling." (PMID 33363463, 2020). "In this study, we provide evidence that CXCL12/CXCR4/PI3K/Akt cascade may be critical for colon cancer cells to metastasize." (PMID 31500630, 2019). "CXCL12 was found to enhance the invasion of colon cancer cells in a concentration-dependent manner." (PMID 31500630, 2019). "Based on our findings, we speculate that PTEN suppresses cell growth, at least in part, through disturbing the function of CXCL12 in colon cancers." (PMID 31500630, 2019).
colon carcinoma (continued). "Furthermore, our study provided data to demonstrate that phosphatidylinositol MAPK/PI3K/AP-1 signaling pathway plays an important role in CXCL12 simulation and that this process is involved in the development and metastasis of colon cancer." (PMID 29305742, 2018). "Human colon cancer cells were transfected with CXCL12 siRNA carrying by Lipofectamine 2000." (PMID 29305742, 2018). "Our results suggest that specific inhibition of CXCL12 may be a convenient and effective way to treat expression CXCL12 of colon cancer patients with expression of CXCL12." (PMID 29305742, 2018). "In conclusion, the CXCL12 gene silencing can significantly inhibit the metastatic potential of colon cancer by siRNA interference, and its mechanism may be related to CXCL12 siRNA down-regulate the cascade of MAPK/PI3K/AP-1 pathway." (PMID 29305742, 2018). "However, the pattern and function of CXCL12 expression remain controversial, because other studies have reported that CXCL12 expression was increased in colon carcinomas or adenomas." (PMID 28418886, 2017). "Thus, HDAC inhibitors of different pharmacological classes restore and/or induce CXCL12 expression in human colon cancer cell lines." (PMID 28418886, 2017). "Finally we identified loss of PCAF expression in tumor samples and showed that forced expression of PCAF in colon cancer cell lines restored CXCL12 expression." (PMID 28418886, 2017). "Together, these data establish that the decreased expression of CXCL12 is an early and frequent event in human colon tumors which does not result from allelic loss." (PMID 28418886, 2017). "Furthermore, CXCL12 expressed by colon cancer metastasis to the liver was demonstrated to promote crosstalk between cancer cells and macrophages, inducing tumor-favorable GM-CSF/HB-EGF paracrine loop." (PMID 25526031, 2014). "Thus, the CXCL12/CXCR4 interaction permits extravasation of colon tumor cells in the liver parenchyma." (PMID 24629239, 2014). "Bim-depleted cells were then examined to test the hypothesis that Bim regulates anoikis sensitivity in colonic carcinoma cells producing CXCL12." (PMID 20877573, 2010). "Therefore, our working model is that endogenous expression of CXCL12 by colonic carcinoma cells interrupts metastasis in part through increased anoikis sensitivity." (PMID 20877573, 2010). "The dichotomy in CXCL12 functions in anoikis potentially reflects a difference between transient and constitutive chemokine expression, as tonic chemokine production elicited anoikis in distinct colonic carcinoma cell lines." (PMID 20877573, 2010). "The ligand CXCL12 significantly increased in the CT-treated tumor and decreased with the combined treatment with Pep R. This could reflect an autocrine loop previously demonstrated in colon cancer cells in which the CXCR4-CXCL12 axis controls cell growth." (PMID 32708431, 2020). "CXCL12/CXCR4/PI3K/Akt cascade may be critical for colon cancer cells to metastasize." (PMID 31500630, 2019). "The present study aimed to analyze the underlying mechanism by which CXCL12 and tumour suppressor protein phosphatase and tensin homologue deleted on chromosome 10 (PTEN) influences the metastatic potential of colon cancer and internal relation of colon cancer and stromal cells." (PMID 31500630, 2019). "Western blot results showed that DLD-1cells transfected with CXCL12 siRNA inhibited the expression of CXCL12 proteins, indicating that the effect of silencing target gene was significantly, this result provided a basis for detecting changes in the biological activity of colon cancer cells." (PMID 29305742, 2018). "In addition, the relationships of phosphorylation of components of MAPK/PI3K/Ap-1 signaling pathway with CXCL12 were examined in this study, and the correlative mechanism for the inhibitive effect of CXCL12 siRNA on the proliferation and invasion of colon cancer cells was investigated." (PMID 29305742, 2018).
colon carcinoma (continued). "The tumor suppressive properties of CXCL12 may be translatable to the clinic as we have shown that administration of the recombinant protein provides an equally strong survival benefit in a preclinical colon cancer model." (PMID 24594697, 2014). "Specifically, triptolide reduces TAM infiltration in colon cancer (HT-29 and CT26) cells by down-regulating CXCL12 gene and protein expression via the NF-κB-ERK1/2 signaling axis, while delaying M2 polarization." (PMID 40490812, 2025). "Highly expressed in colon cancer, CD164 drives proliferation and metastases along the CXCL12 (SDF-1)/CXCR4 signaling axis." (PMID 40692786, 2025). "Several chemokines such as CXCL1, CXCL12, and CXCL2 as well as CXCL17 were involved in the development, growth, and progression of the colon cancer." (PMID 35607443, 2022). "The expression of CXCL12 and its ligand CXCR4 are independent prognostic factors for the 5‐year disease‐free survival rate of patients with colon cancer." (PMID 35363937, 2022). "In recent studies, we established that CXCR4 antagonist MSX-122 (substituted pyrimidine-2-amine) blocked CXCL12-induced EGFR transactivation and colon cancer progression in azoxymethane-induced mouse model." (PMID 34298991, 2021). "The expression of CXCR4 in colon cancer cells after treating with stromal cell-derived factor-1α (SDF-1α, or CXCL12) was investigated, along with the cancer cell proliferation rate and chemosensitivity to 5-FU, irinotecan, and oxaliplatin." (PMID 35582377, 2021). "To explore the role of senescent tumor cells in macrophage polarization, we cocultured isolated primary monocytes with colon cancer cells (SW480), ROS induced senescent tumor cells (SW480/ROS), CXCL12, and/or CSF1 overexpressing cells." (PMID 33643790, 2021). "Improvement in antiPD1 function was revealed in murine colon cancer models by combined treatment with Pep R and NOXA-012, CXCL12-targeting antagonists." (PMID 32708431, 2020). "RT-PCR and western blot were detected the expression of CXCL12, CXCR4 and PTEN in colon cancer cells and stromal cells." (PMID 31500630, 2019). "The expression of PTEN, CXCL12 and CXCR4 mRNA and protein were detected in colon cancer cell lines and stromal cells using RT-PCR and Western blot." (PMID 31500630, 2019). "We used the colon cancer cell lines to examine the activation of the PI3K/Akt signaling pathway, a downstream target of CXCl12." (PMID 31500630, 2019). "In summary, we have demonstrated that stromal cell-derived CXCL12 to activate PI3K/Akt pathway by down-regulating PTEN leads to enhanced proliferation and invasion in colon cancer cells." (PMID 31500630, 2019). "The co-operative effects of CXCL12 and PTEN on proliferation and invasion of colon cancer cells were evaluated by real-time PCR, proliferation and invasion assays using an in vitro system consisting of co-cultured cancer cells and stromal cells." (PMID 31500630, 2019). "We eventually investigated activation of PI3K/Akt signaling by CXCL12 regulate PTEN and involved in the metastatic process of colon cancer." (PMID 31500630, 2019). "Western blot showed that CXCL12 protein was only expressed in DLD-1 cells, and CXCR4 was expressed in four colon cancer cell lines." (PMID 29305742, 2018). "After being transfected with CXCL12 siRNA and Control siRNA for 24 h, HT-29 and DLD-1 colon cancer cells were cultured for 72 h, and the proliferation of cancer cells was measured by WST-1 assay." (PMID 29305742, 2018). "To further investigate CXCL12 gene silencing influence on tube formation by HUVEC, we co-cultured with colon cancer cell and HUVEC/fibroblast using double-chamber methods to determine the interaction among them." (PMID 29305742, 2018). "Illumina methylome arrays of 87 colon carcinomas (40 MSS and 47 MSI tumors) were used to investigate CXCL12 promoter methylation." (PMID 28418886, 2017).